PDK1 (pyruvate dehydrogenase kinase 1)
Diseases named in the same sentence as PDK1 in open-access papers (continued):
Sharing a sentence is not in itself a finding about the gene and the disease.
tumor (continued). "Furthermore, we demonstrate that the expression of PDK1, PHD3, and HIF-1α proteins in NB tumor samples can be used in immunohistochemistry to evaluate the hypoxic status of NB tumors, and could, therefore, be successfully used as a relevant tool to stratify high-risk patients." (PMID 29117193, 2017). "By focusing on PDK1, the LIN28 A/B, and let-7g axis modulates the Warburg effect to stimulate tumor proliferation in a way that is independent of the hypoxia-inducible factor (HIF-1)." (PMID 39170516, 2024). "No significant statistical relationship existed between PDK1, PDK2, and PDK3 expression and tumor grade (P = 0.257, P = 0.395, P = 0.544)." (PMID 34220962, 2021). "Moreover, the downregulation of phosphorylation of the primary PDK1 target Akt, which has been reported in several celecoxib-treated tumour cell lines, is not consistently observed in all tumour cells, even though apoptosis is similarly induced by drug treatment." (PMID 17955049, 2007). "Interestingly, MAPK4 was demonstrated to promote tumours through direct and specific activation of AKT/mTOR via an alternative pathway without dependence on PI3K/PDK1." (PMID 40845073, 2025). "Together, these data suggest that while MAPK4-induced PDK1 protein expression (MAPK4-PDK1 axis) alone is not sufficient to robustly promote AKT phosphorylation/activation and tumor cell growth, it does provide a route to enhance the tumor-promoting activity of activated AKT." (PMID 37531320, 2023). "A combination of genetic and chemical genetic experiments demonstrate that these defects are due to the loss of the lipid phosphatase activity of PTEN and to the activation of 3-phosphoinositide-dependent protein kinase-1 (PDPK1 (PDK1)), but do not depend on the AKT-mTOR tumor suppressor pathway." (PMID 26809587, 2016). "Similarly, cells expressing exogenous PDK1 developed into tumors with ~70% smaller volumes than observed with the corresponding control cells at day 25, and PDK1 overexpression in RNF126-depleted cells did not decrease the tumor volumes further." (PMID 27462466, 2016). "Although PDK1 transgenic mice did not exhibit changes in mammary gland development, function and tumorigenicity, they were markedly sensitive to GW501516 treatment, where median tumor-free survival was reduced four-fold in comparison to a two-fold reduction in GW501516-treated wild-type mice." (PMID 21297860, 2011).
cancer (425 papers, 2005 to 2026). A tumor composed of atypical neoplastic, often pleomorphic cells that invade other tissues. "Although no PDK1-activating mutations have been identified in tumors to date, PDK1 is frequently overexpressed in various human cancers, where its upregulation drives tumorigenesis and progression." (PMID 40482916, 2025). "Pan-cancer analysis confirms PDK1’s overexpression and poor prognosis association in multiple malignancies." (PMID 40971960, 2025). "This mutation seems to result in PDK1 upregulation, potentially contributing to the altered metabolism observed in cancer cells." (PMID 38689087, 2024). "Collectively, these findings indicate that elevated PDK1 levels are associated with cancer progression and osimertinib resistance mechanisms." (PMID 38689087, 2024). "Pyruvate dehydrogenase kinase 1 (PDK1) is a key enzyme overexpressed in metabolic reprogramming of many cancers, and is associated with bad prognosis and resistance to therapy." (PMID 37612452, 2023). "PDK1 is a crucial glycolytic enzyme closely associated with cancer cell proliferation, metastasis, and chemoresistance." (PMID 37980488, 2023). "The hyperactivation of Akt, downstream of PDK1, is a hallmark of many human cancers, as well as a number of rare overgrowth disorders and immune diseases." (PMID 35387990, 2022). "HIF1α-dependent induction of PDK1 is associated with glycolytic reprogramming, enhanced cancer cell proliferation and stemness in several tumors." (PMID 36340043, 2022). "In echoing the important roles of CK1 and GSK3β-mediated PDK1 phosphorylation and degradation, patients-associated mutations S390L, S394L and S398L were identified in cancer patients." (PMID 34353330, 2021). "Increasing pieces of evidence have shown that the expression of PDK1 is dysregulated in multiple cancer types, and PDK1 is implicated in signaling pathways frequently altered in cancer." (PMID 35082773, 2021). "PDK1 has also been implicated in cancer invasiveness as it plays a significant role in cell migration and invasion, especially in three-dimensional environments." (PMID 34768921, 2021). "PDK1 has been implicated in cancer progression, including proliferation, apoptosis and invasion and involved in signaling pathways altered in cancer, such as PI3K/Akt, Ras/MAPK and Myc." (PMID 33425771, 2020). "Studies have reported that HIF1-induced LDHA and PDK-1 cause the Warburg effect, which enhances glucose metabolism in cancer cells." (PMID 31936895, 2020). "Involvement of PDK1 has also been implicated in cancer cell epithelial–mesenchymal transition (EMT) and metastasis, for example in metastasis of liver aggressive 4T1 breast cancer (BrCa) cells to the liver, which implies an oncogenic role." (PMID 33384955, 2020). "Of note, Lin28 expression is strictly linked to metabolism since it is able to regulate cancer cell progression via PDK1 and to induce an energetic switch." (PMID 31109089, 2019). "Evidence is also emerging indicating that PDK1 inhibition can impact on several cellular functions associated with cancer progression, such as reduced invasion on Matrigel of breast, prostate and melanoma cancer cell lines." (PMID 31088502, 2019). "Being part of the pathway PDK1 is also implicated in cancer, in the majority of the cases though it is the overexpression that leads to pathologic conditions, rather than mutations." (PMID 29064423, 2017). "Activation of PI3K signaling via PDK1 kinase has been implicated in cancer, and PDK1 has been found to regulate cell growth, proliferation, and migration." (PMID 27474797, 2016). "Constitutive activation of the PDK1/PKB signaling cascade is a hallmark of highly invasive cancers, and viruses exploit it to extend the lifespan of infected cells under stress." (PMID 25742010, 2015). "Taken together, our results imply that the trafficking of active Src to autophagosomes in FAK-deficient cancer cells is controlled by the PDK1/Akt/p70S6K pathway." (PMID 26071201, 2015).
cancer (continued). "Enhanced glucose uptake through GLUT1 and increased aerobic glycolysis through LDHA and PDK1 is the hallmark of cancer cells." (PMID 26484566, 2015). "Based on our results, we show that inhibition of PHD2 by DKG increases the expression of genes implicated in the glycolytic pathway (GLUT1 and PDK1), the mechanism known to play an important role in cancer progression." (PMID 25420025, 2014). "Introduction of a hypomorphic mutation of PDK1 in a PTEN cancer mouse model suppresses tumorigenesis, confirming the oncogenic role of PDK1 as one of the downstream effectors of the PI3K/PTEN signaling, and suggesting PDK1 as a promising anticancer target." (PMID 22666248, 2012). "The roles of PDK-1 in human cancers were implicated by the finding that overexpression of PDK-1 transformed mammary epithelial cells." (PMID 16288304, 2005). "PDK1 expression is associated with oncogenic activity in cancer progression." (PMID 39578715, 2024). "Notably, these genes, such as PPARG, HK2, and PDK1, play critical roles in the regulation of aerobic glycolysis in cancer cells, which is associated with the IDH phenotype in GBM cells." (PMID 39530009, 2024). "Consequently, PDK1 dysregulation provokes diverse cellular consequences, including enhanced growth, migration, and cell survival—processes associated with cancer in animals." (PMID 37961644, 2024). "Biologically, knockdown PDK1 could significantly decrease mutated SPOP-induced cancer cell malignant phenotypes." (PMID 34353330, 2021). "MAPK, PEA15, and PDK1 were closely associated with cancer metastasis." (PMID 33842538, 2021). "High PDK1 expression was associated with cancer metastasis and poor patient outcomes." (PMID 32071289, 2020). "PDK1–4 have been associated with therapy resistance in several cancers." (PMID 33384955, 2020). "Considering the important role of PDK1 in the migration of cortical excitatory neurons and cancer cells, we next examined whether the reduction of cortical interneurons in the Pdk1 cKO cortex was caused by defects of tangential migration." (PMID 32366272, 2020). "Inhibition of Pgp expression may be related to celecoxib’s many off-target effects, such as inhibition of cancer-associated carbonic anhydrases, the master kinase PDK1, or the sarco/endoplasmic reticulum Ca2+-ATPase." (PMID 32365663, 2020). "PDK1–3 are described as oncogenes in different cancer types where their high expression is associated with EMT and metastasis, higher proliferation and migration, and most relevantly with therapy resistances, such as to 5-FU in CRCa and GCa, cisplatin in HNSCCa and OCa or paclitaxel in NSCLCa." (PMID 33384955, 2020). "Indeed, while for many years the potential role of this enzyme in cancer was almost exclusively associated with its regulatory role on Akt activation, several recent data have revealed additional roles for PDK1, independently of Akt activation." (PMID 31088502, 2019). "Finally, 41 missense substitutions had been found in PDK1 linked to various types of cancers (Cosmic database)." (PMID 31601855, 2019). "Among the four PDK isoforms, PDK-1 implicated into malignancy cancer." (PMID 30988063, 2019). "Lately, many cases have been reported where PDK1 is directly or indirectly implicated in chemoresistance, with its inhibition resulting in re-sensitization of cancer cells to chemotherapeutic agents, and this is going to be the topic of discussion in the following sections." (PMID 29064423, 2017). "Since PDK1 is overexpressed in several cancers, it might provide a causal link between chronic inflammation and malignant cellular transformation." (PMID 26889381, 2016). "Accordingly, human cancers frequently display somatic mutations affecting PI3K /PDK1/PKB signaling." (PMID 25742010, 2015).
cancer (continued). "However, many additional molecules, including pyruvate dehydrogenase kinase-1 (PDK-1), are involved in cancer cell-associated processes including active glycolysis, mitochondrial dysfunction and glucose uptake." (PMID 23135628, 2013). "This review summarizes recent progress in comprehending PDK1's structure, regulation, and its function in oncogenic (cancer-promoting) signaling." (PMID 41928774, 2026). "Reportedly, phosphorylation of enzymes by tyrosine kinases, such as pyruvate dehydrogenase kinase 1, can disrupt mitochondrial pyruvate metabolism in cancer cells." (PMID 40601671, 2025). "Collectively, we propose a novel approach based on PDK1 degradation for cancer therapy to enhance immunoreactivity." (PMID 40873633, 2025). "In this study, we harnessed PROTAC technology to target the aberrantly expressed metabolic enzyme PDK1 in cancer cells, creating degrader compounds based on the classical PDK inhibitor DCA." (PMID 40873633, 2025). "As an essential limiting enzyme for glycolysis, PDK1 can efficiently phosphorylate pyruvate dehydrogenase (PDH), promoting aerobic glycolysis in cancer cells and reducing cell damage caused by ROS accumulation." (PMID 40971960, 2025). "The activation of the PDK1-AKT axis is a well-established hallmark governing cell proliferation, survival, drug resistance, and metabolism in various cancers." (PMID 41369408, 2025). "In this study, the anti-cancer effect of FTO is consistent with its function as an m6A demethylase—low expression of FTO enhances the m6A modification of PDK1 mRNA, thereby stabilizing PDK1 and activating the pro-cancer AKT/mTOR pathway." (PMID 41145484, 2025). "The role of PDK1 in cancer metabolism underscores its significance as both a prognostic biomarker and a therapeutic target." (PMID 40971960, 2025). "Pan-cancer analysis extended the findings to other cancer types, confirming that PDK1 is overexpressed in multiple malignancies and generally associated with poor prognosis." (PMID 40971960, 2025). "PDK1 is recognized as a critical regulator of glycolysis and serves as a targetable determinant of various metabolic states in cancer." (PMID 41465397, 2025). "Serving as a key glycolysis‐related enzyme downstream of HIF‐1α during hypoxic conditions, the role of PDK1 in regulating EMT has been documented in various cancers." (PMID 40176272, 2025). "Their ability to disrupt cancer pathways—such as PDK1/Akt, MAPK/ERK1/2, and Akt/mTOR—alongside their role in apoptosis induction and angiogenesis inhibition, highlights their therapeutic versatility." (PMID 40718442, 2025). "AKT can be activated by PDK1 and mTOR, and over-activation of AKT can cause proliferation and survival of cancer cells." (PMID 40374533, 2025). "In conclusion, we first utilize PROTAC technology on modulating aberrant expressed metabolic enzyme PDK1 in cancer cells and achieve a great pharmacological effect, rendering it promising for energy‐aberrant cancer therapy." (PMID 40873633, 2025). "It was shown that LNCaP cells had higher cyclin‐dependent kinase inhibitor 1A (CDKN1A) expression and lower 3‐phosphoinositide‐dependent kinase 1 (PDK1) expression, both of which have been connected to the development of cancer." (PMID 41179368, 2025). "HIF-1α-induced upregulation of PDK1 inhibits PDC activity, causing a shift in the cancer cell metabolism towards anaerobic glycolysis, and decreases the production of ROS." (PMID 38255882, 2024). "For instance, metformin not only downregulates the expression of PDK1 to overcome cisplatin resistance but also reduces the levels of HIF-1α in drug-resistant cancer cells and interferes with the transcription of glucose metabolism-related genes." (PMID 38577616, 2024). "PDK1, a pyruvate dehydrogenase kinase family member related to oncogenic pathways, is overexpressed in diverse cancers and is valuable in targeted cancer therapy." (PMID 39578715, 2024).
cancer (continued). "Research has indicated that CAFs stimulate the elevation of pyruvate dehydrogenase kinase 1 (PDK1) expression in cancer cells through proteins secreted within the TME." (PMID 38903506, 2024). "PKM2 can also function as a coactivator that stimulates hypoxia-inducible factor 1 (HIF-1) transactivation of target genes encoding PDK1, LDHA, and Glut1 in cancer cells." (PMID 38725851, 2024). "As the gatekeeper of the Warburg effect, PDK1 modulates metabolic reprogramming by regulating pyruvate dehydrogenase complex activity and is a promising therapeutic target in many cancers." (PMID 38560503, 2024). "Hypoxia-inducible factor 1-alpha and PDK1 are master regulators for hypoxic responses and cancer metabolism." (PMID 38311175, 2024). "G6PD and PDK1 are known to regulate the Warburg Effect, a phenomenon in which cancer cells preferentially use glycolysis for energy production." (PMID 38351531, 2024). "STAMBP knockdown decreased PDK1 levels, an essential regulator of the aerobic glycolytic process, in several cancers." (PMID 39242557, 2024). "Cancer cells exhibit high levels of PDK1 expression and activity, which promotes glycolysis and facilitates cancer cell survival and proliferation." (PMID 38255882, 2024). "Previous studies have demonstrated that inhibiting PDK1 can enhance the anticancer effect of EGFR-TKIs in malignant tumors, including NSCLCs16,17." (PMID 38689087, 2024). "Our study established a clear link between the EGFR C797S mutation and elevated PDK1 expression, opening new avenues for the discovery of targeted therapies and improving our understanding of the roles of EGFR mutations in cancer progression." (PMID 38689087, 2024). "During the last few decades, the inhibitions of the PDK1-AKT cascade have shown great potential as a target for cancer therapy." (PMID 37107587, 2023). "The RAF/MEK/ERK and PI3K/PDK1/AKT signaling axes exert critical influences in cancer and have become new targets for cancer therapy." (PMID 37259393, 2023). "Encouragingly, the use of PDK1 inhibitors in cancer treatment has shown significant efficacy in regulating the growth and survival of cancer cells." (PMID 38035024, 2023). "Despite the demonstrated effectiveness of several small molecules as PDK1 and Akt inhibitors both in vitro and in vivo, only a few have progressed to clinical trials for cancer treatment purposes." (PMID 38035024, 2023). "PDK1 is involved in the regulation of various cancer signaling pathways and can also be involved in the regulation of aging." (PMID 37828220, 2023). "As an important member of the PI3K signaling pathway, PDK1 has been considered a target for anti-cancer drug development." (PMID 37311034, 2023). "HIF-1α-mediated PDK1 activation results in the preference of cancer cells towards aerobic glycolysis." (PMID 37759534, 2023). "The PAM signaling pathway involves numerous feedback loops, compensatory pathways, and crosstalk nodes with other signal transduction axes that hamper the inhibition of PI3K, AKT, mTORC1, mTORC2, and PDK1 in cancer." (PMID 37596643, 2023). "Aberrant activation of downstream effectors of PDK1 and alterations in PDK1 itself have been reported in the context of cancer, which can lead to a poor prognosis and shorter overall survival." (PMID 38035024, 2023). "PDK1 expression is dysregulated in many cancer types and is an interesting and unexplored target for cancer therapy." (PMID 37828580, 2023). "This study shows that besides activating AKT, MAPK4 promotes PDK1 protein synthesis and thus also activates PDK1 substrates beyond AKT to promote cancer." (PMID 37531320, 2023). "Meanwhile, TIPE promotes vascular endothelial growth factor receptor 2 (VEGFR2)-mediated angiogenesis by upregulating the expression and phosphorylation of pyruvate dehydrogenase kinase 1 (PDK1) in cancer cells, thus promoting metastasis." (PMID 37369681, 2023).